CXCL10 (C-X-C motif chemokine ligand 10)
Diseases named in the same sentence as CXCL10 in open-access papers (continued):
Sharing a sentence is not in itself a finding about the gene and the disease.
tumor (continued). "Type I IFNs aid in chemotherapy-induced ICD mainly through autocrine or paracrine signaling cascade, elicit immunostimulatory effect via IFNAR signaling in immune cells, and trigger CXCL10 secretion by tumor cells." (PMID 36755812, 2022). "Chemokines, such as CXCL9 and CXCL10, serve as key factors that recruit Teffs into the center of the tumor, further promoting antitumor immunity and disrupting tumor cell proliferation and invasion." (PMID 35488336, 2022). "This rescue of the tumor growth was associated with significantly decreased CD8+ T cell infiltration, suggesting that CXCL10-mediated CD8+ T cell infiltration played a crucial role in L. paracasei sh2020-induced tumor inhibition." (PMID 35259052, 2022). "Previous studies demonstrated that tumor cell-derived CXCL9/CXCL10 modulated T-cell recruitment in various tumors." (PMID 36284313, 2022). "We found that the protein levels of CXCL9 and CXCL10 were obviously elevated, and the protein level of caveolin-1 was downregulated in the tumor cells of mice treated with anti-GD2 mAb plus MβCD compared with the other three groups." (PMID 36284313, 2022). "We further reveal that the CXCL10/CXCR3 signaling of tumor cells is augmented via an autocrine pathway." (PMID 36612121, 2022). "In particular, CXC ligand 1 (CXCL1), CXCL10 and CXCL13 have recently been associated with tumor survival, metastasis and angiogenesis." (PMID 36077611, 2022). "Meanwhile, CXCL10 has been shown to induce tumor progression and metastasis through CXC motif chemokine receptor 3 (CXCR3) in melanoma, colon cancer, and breast cancer." (PMID 36612121, 2022). "Differentially expressed cytokines (CCL5, CCL19, CXCL9 and CXCL10) were related to the overall survival, and their expression levels were also examined both in tumor tissues of CL-BCa patients by IHC and in typical CL-BCa cell lines by qPCR." (PMID 35359417, 2022). "Expression of CXCL10 upon encounter of tumor antigens in a synthetic notch receptor (synNotch) steered manner improved subsequent CXCR3-based tumor infiltration by CAR T cells." (PMID 36366354, 2022). "CXCL10 from BAL fluid significantly decreased when tumors developed; however, EGFR-TKI treatment increased CXCL10 expression levels according to tumor regression." (PMID 36612121, 2022). "In vivo, significant modulation of cytokine gene expression (particularly CCL2 and CCL5, and C-X-C motif chemokine ligand 10) was observed, with in vitro data indicating that CCL2, CCL5, and CXCL10 were produced by tumor cells after ATR inhibition plus RT." (PMID 36612206, 2022). "As observed in other tumor entities, CXCL10 modulates leukocyte migration to the tumor site thereby governing anti- or pro-tumorigenic activity." (PMID 35897689, 2022). "The expression of CXCL10 in tumor blood vessel endothelial cells is increased by Treg depletion, leading to further promotion of T-cell migration into tumors." (PMID 35935996, 2022). "Previous studies have also reported that CXCL10 exhibits anti-neoplasm activity by inhibiting angiogenesis and increasing the fraction of TIICs." (PMID 35755810, 2022). "Since these effects are not dominant in vivo, there must be another player supporting these Cxcl10-dependent effects on tumor progression." (PMID 35897689, 2022). "CCL19 binds to CCR7 on a multitude of cell types including DCs and T-cells, whereas CXCL10 is a is a canonical chemokine for attracting T-cells, and its upregulation is correlated with smaller tumor size." (PMID 36741387, 2022). "In vitro and in vivo data demonstrated that ATRi plus RT promoted the production of CCL3, CCL5, and CXCL10 in tumour cells." (PMID 35365161, 2022). "Decreased expression of CXCL9 and CXCL10 renders EOC cells resistant to anti-tumor T-cell infiltration and eventually leads to immune escape." (PMID 35269786, 2022). "Targeting the tumor microenvironment via CXCL10 is a potential novel therapeutic option for improving the efficiency of cancer therapies in HCC." (PMID 35897689, 2022).
tumor (continued). "CXCL10 siRNA treatment of EGFR-mutant tumor cells also decreased CXCL10 in the supernatant from coculturing with activated PBMCs, suggesting that the effects of CXCL10 occur via autocrine and paracrine pathways." (PMID 36612121, 2022). "IFNα treatment facilitates lymphocyte infiltration into tumors through augment of CXCL10 production by tumor cells." (PMID 35145233, 2022). "It has been reported CXCL10 exert anti-malignancy function by inhibiting angiogenesis and influencing tumor microenvironment." (PMID 36207693, 2022). "The binding of CXCL10 with CXCR3-B can inhibit tumor cell proliferation, migration and suppress the immune responses." (PMID 35083488, 2022). "Cooperation between PRC2 and DNMT1-mediated DNA methylation was shown to suppress the expression of T helper 1 (Th1)-type chemokines CXCL9 and CXCL10 to impede tumor infiltration of CD8+ T cells." (PMID 36323669, 2022). "CXCL10 appears to have dual effects on tumor progression which depends on the type of CXCR3 receptor." (PMID 35083488, 2022). "Generally, CCL17 weakly and positively correlated with early factors of tumour grow (CXCL10), but then weakly and negatively correlated with late factors of tumour growth (myeloid cell populations); CXCL1 and CCL2 acted like CCL17 in this respect." (PMID 35226704, 2022). "In this scenario, IFNα-MSCs in tumor sites induce the production of CXCL10 in tumor cells which in turn mobilizes CD8+ T cell into tumors." (PMID 35145233, 2022). "This points to the overall tumor promoting effect of CXCL10 in the respective cell types during HCC progression." (PMID 35897689, 2022). "Further, recent studies have shown that TLS promotes recruitment of lymphocytes to the tumor microenvironment by expressing chemokines such as CXCL10, CCL19 and CCL2131." (PMID 35027623, 2022). "Considering this, we confirmed that L. paracasei sh2020 treatment confers high levels of CXCL10 than the control tumor in both vitro and vivo." (PMID 35259052, 2022). "The IP10/CXCL10 was shown to mediate interactions between tumor and stromal cells and to organize leukocyte trafficking and angiogenesis which results in the induction of metastasis." (PMID 36012769, 2022). "In mice, IFN-γ promoted CXCR3 expression on NK cells and also enhanced the production of its ligands, CXCL9 and CXCL10, on virus-infected cells and tumor cells;183,255 these ligands are important for NK cells’ anti-infection and anti-tumor properties." (PMID 35768424, 2022). "The most striking alteration in the Cxcl10−/− tumor immune microenvironment was a vast accumulation of anti-tumoral T cells in the invasive tumor margin." (PMID 35897689, 2022). "We report that PAK4 inhibition reverses immune cell exclusion by increasing the infiltration of CD8 T cells and CD103+ dendritic cells (DC), a specific type of DCs that excel at cross-presenting tumor antigens and constitute a source of CXCL10." (PMID 36588582, 2022). "CXCL10 has long been known to exert anti-malignancy functions by influencing the tumor microenvironment." (PMID 34422627, 2021). "On the other hand, PBAF inactivation promotes the secretion of chemokines CXCL9 and CXCL10 by tumor cells, which contributes to the increased recruitment of Teff cells to the tumor microenvironment." (PMID 33746989, 2021). "Further comprehensive analysis of the tumor immune microenvironment (TIME) revealed that the expression of CXCL10 was positively correlated with neoantigen load and infiltrating immune cells." (PMID 34158843, 2021). "In a mouse model of LLC, deletion of cancer-associated miR-21 in TAMs led to the increased tumor cell death and inhibition of neovascularization mediated by TAM-produced CXCL10 and IL-12." (PMID 34209679, 2021). "Mice with A549 adenocarcinoma or NSCLC treated intratumorally with CXCL10 showed a reduction in tumor size, angiogenesis, and metastasis." (PMID 34503058, 2021).
tumor (continued). "The quantitative measurement of CXCL10 abundance in tumours is further complicated by numerous potential post-translational events, in particular the enzymatic cleavage of its N-terminal Val-Pro dipeptide." (PMID 34200333, 2021). "As depicted in the scatter plot, the CXCL10 upregulation correlated to the infiltration of dendritic cells and anti-tumor lymphocyte subpopulations (Spearman's rank correlation coefficient, P < 0.0001)." (PMID 34158843, 2021). "There were significant differences in CXCL10 expression between the tumor stages IV and I, ranging from low to high." (PMID 34559115, 2021). "When tumor cells produce EMT, they often secrete more cytokines such as CXCL9 and CXCL10, which can inhibit the function of NK cells, thus promoting tumor immune escape." (PMID 33992097, 2021). "This concurs with the result of a previous study that CXCL10 not only acts to tumor microenvironment through paracrine signaling but also in an autocrine manner, giving a self-signal for proliferation and migration." (PMID 34504204, 2021). "In contrast, DPP4 inhibition enhanced tumor rejection by preserving the full-length biologically active form of CXCL10, leading to increased trafficking of CXCR3+ cells into the TME." (PMID 33757558, 2021). "Recently it has also been shown that at the tumor site TGF b suppresses CXCR3 expression by CD8+ T cells thus enabling tumors to escape CXCL10 induced recruitment to the tumor site." (PMID 34944943, 2021). "We further analyzed the correlation between CXCL10 and immune cells infiltrating the tumor microenvironment using the TIMER database." (PMID 33345267, 2021). "The finding is of significant interest to the field, challenging the paradigm that the effects of CXCL10 are anti-tumor immune responses through immunosuppressive mechanisms, including upregulated expression of PD-L1." (PMID 34422627, 2021). "MDSCs and CXCL10/TLR4 levels were significantly increased in patients with GWR <60% or tumor recurrence." (PMID 33990548, 2021). "The inhibition of DPP4 preserves the CXCL10 chemokine and enhances the tumor immunity and the migration of T-cells to the tumor microenvironment." (PMID 35087404, 2021). "Interferon gamma-induced protein (IP-10), also known as, CXCL10, is an immunomodulatory cytokine associated with lymphocytic infiltrate to the tumor site." (PMID 34604026, 2021). "TAM-derived prostaglandin E2 (PGE2) initiates the production of CXCL12, which induces myeloid-derived suppressor cell (MDSC) accumulation and inhibits the production of CXCL10, a chemokine that activates anti-tumor immunity." (PMID 34209703, 2021). "Combination therapy using cisplatin and cGAMP enhances the gene expression of CXCL9 and CXCL10 in tumor tissues and inhibits tumor growth." (PMID 34830754, 2021). "DDP4 cleaves CXCL10 chemokine which is important in determining the trafficking of effector T-cells to the tumor microenvironment." (PMID 35087404, 2021). "Single cell RNA sequencing data confirm the existence of a tumor-infiltrating CXCL10+IRF1+STAT1+ M1-type TAM overexpressing antigen processing and presentation gene programs." (PMID 34220848, 2021). "CXCL10 is an important pro-inflammatory cytokine and has been reported to mediate the mobilization of tumor-inhibitory CXCR3+ T cells, as well as natural killer cells, into solid cancers." (PMID 34336848, 2021). "CXCL9 and CXCL10 are the major Th1 chemokines responsible for T cell recruitment to the tumor microenvironment." (PMID 33403469, 2021). "Compared with the corresponding control and wild-type CC cells, SW480-CXCL10 and SW620-CXCL10 cells formed more tumor metastases in the lungs of nude mice, indicating that upregulation of CXCL10 expression increased the incidence of lung metastases." (PMID 34345201, 2021). "Labelling was profuse within the tumor in control condition and the inoculation of GlioGel with chemokines, especially with CXCL10, produced an increase in the marking." (PMID 34830041, 2021).
tumor (continued). "It is therefore likely that the increased expression of CXCR3 seen on the T cells in draining lymph node in vivo is in response to paracrine CXCL9 and CXCL10 signals possibly from the tumor." (PMID 34336705, 2021). "Our mouse cytokine array analyses showed that SIRT6 over‐expression in the skeletal muscle significantly inhibited plasma levels of CXCL10 in the tumour‐bearing mice." (PMID 34212132, 2021). "It has been suggested that CXCR3+ regulatory T cells are attracted to the tumor microenvironment as a result of intratumoral CXCL10 secretion." (PMID 34203869, 2021). "In this cohort, tumor patients with high CXCL10 expression exhibited markedly improved clinical benefits and significantly prolonged survival." (PMID 34158843, 2021). "PBAF-deficient tumor cells efficiently responded to IFN-γ by enhancing chemokines, including CXCL9 and CXCL10, which led to the accumulation of effector T cells." (PMID 34827646, 2021). "Consistent with our in vitro studies, mice treated with free cGAMP showed rapid Ifnb1/Cxcl10 expression 6 h after intratumoural injection, while the activity decreased considerably over 48 h in both tumour and nodal tissues." (PMID 33558734, 2021). "Conversely, high expression of CXCL10 and CXCR3 in the tumor microenvironment has been shown to be associated with a poor prognosis in human PDAC in several studies." (PMID 34203869, 2021). "Even if we observed a slight increase in cell proliferation with the Ki-67 staining when GlioGel with chemokine was inoculated in the tumor, the same process induced a drastic fall in the number of peritumoral clusters, especially with CXCL10." (PMID 34830041, 2021). "For example, in vivo inhibition of the protease CD26 resulted in elevated concentrations of intact CXCL10 accompanied by enhanced anti-tumor activity in mice." (PMID 33777041, 2021). "In NPC, immunohistochemistry showed the presence of CXCL10-positive neoplastic cells in the majority of tumours, as well as CXCR3-positive lymphocytes in the accompanying stroma." (PMID 34956172, 2021). "Mettl3- or Mettl14-deficient tumors increased cytotoxic tumor-infiltrating CD8+ T cells and elevated secretion of IFN-c, Cxcl9, and Cxcl10 in tumor microenvironment in vivo." (PMID 34804948, 2021). "EZH2-mediated methylation has been demonstrated to repress T helper 1 (Th1) chemokines, CXCL9 and CXCL10, resulting in reduced T-cell recruitment to the tumor microenvironment." (PMID 34140011, 2021). "At tumor sites, eosinophils repolarize macrophages, normalize tumoral blood vessels, and recruit and activate tumor-specific cytotoxic T cells via a CXCL9/CXCL10-dependent mechanism." (PMID 33754022, 2021). "The results showed that the tumor volume and weight after overexpression of CXCL10 were smaller than that of the NC group (P < 0.05)." (PMID 34794429, 2021). "Along the same lines, other studies have linked increase of cytokines, like CXCL9, CXCL10, CXCL11, and CXCL19, under ICIs as a sign of enhanced general immune reactivity with both subsequent tumor responses and development of irAE in NSCLC." (PMID 34268127, 2021). "As we predicted using the database, we first verified the immune effect of CXCL10 through T cell killing experiments and found that overexpression of CXCL10 can promote the killing of tumor cells by T cells." (PMID 34794429, 2021). "High expression of CXCL10 will inhibit the immune response mediated by T cells, leading to an increase in tumor growth rate." (PMID 33767987, 2021). "There was an increased IFN-γ and CXCL10 production in the tumor environment and an influx of CD8+, CD4+ T, and NK cells." (PMID 33803078, 2021). "The treatment of cold tumors with Vps34 inhibitors induces the release of inflammatory chemokines such as CCL5 and CXCL10 in tumor cells, resulting in homing of natural killer (NK) and CD8+ T cells to the tumor microenvironment." (PMID 34680466, 2021).
tumor (continued). "Second, we examined gene expression levels for a selection of chemokines associated with T cell recruitment to the tumor, namely CCL4, CCL5, CXCL9, CXCL10." (PMID 33806316, 2021). "Knockout or inhibition of CXCL10/TLR4 signaling significantly reduced the tumor growth with decreased monocytic MDSCs and MMP14 in the mouse tumor recurrent model." (PMID 33990548, 2021). "After further staining the tumor tissue, it was found that the tumor proliferation ability after overexpression of CXCL10 was weakened, and the cell apoptosis was significantly increased." (PMID 34794429, 2021). "This mast cell LPS-mediated TLR4 activation led to subsequent mast cell secretion of CXCL10, a chemokine that attracts effector T cells to tumors, which then mediate anti-tumor immunity." (PMID 34063789, 2021). "Recently, it has been proposed that tumour cells can reduce CXCL9/CXCL10 gradients by secreting galectin-3, a lectin that blocks IFN-γ diffusion." (PMID 33809369, 2021). "Simultaneously, CXCL9 and CXCL10 have been shown to increase levels of tumor infiltrating CD8+ effector T cells and NK cells, minimize metastasis, and are correlated with improved responses to checkpoint blockade and adoptive cell transfer therapies." (PMID 34012451, 2021). "Of note, we found that a fraction of M1-type TAM in OCs produce abundant CXCL10, likely representing one of the relevant T-cell attracting chemokines in this neoplasm." (PMID 34220848, 2021). "As seen for plasma levels, Cxcl10 mRNA expression was also significantly reduced in gastrocnemius muscle of Tu‐Sk.T6Tg mice, compared with that in Tu‐CN mice, indicating a direct transcriptional regulation of Cxcl10 by SIRT6 in the context of tumour." (PMID 34212132, 2021). "Deregulation of CXCL10 has been related to chronic inflammation, autoimmunity, tumor development, metastatic dissemination and infectious diseases." (PMID 34200459, 2021). "CXCL9/MIG and CXCL10 have been reported to inhibit tumor growth and metastasis of NSCLC and hemangiosarcoma." (PMID 33710817, 2021). "Studies have shown that TGF-β released by tumor cells activated the p38-MAPK pathway in CAFs, increasing the levels of chemokines such as CXCL10, IL-6, and IL-8, thereby inducing glycogen catabolism in tumor cells." (PMID 34512351, 2021). "The results showed that CXCL10 was negatively correlated with tumor purity; this finding suggested that the main source of CXCL10 was stromal cells but not cancer cells." (PMID 34276760, 2021). "Angiogenesis and T cell killing assay were used to detect the effect of CXCL10 on tumor cell immunity and angiogenesis." (PMID 34794429, 2021). "MDA-MB-231 showed similar results as MCF-7: migration of tumor cells in the wounded area seemed to increase when treated with CXCL10." (PMID 34504204, 2021). "Elevated level of circulating CXCL10, as in tumour environment, can trigger β‐cell apoptosis resulting in significant reduction in insulin secretion." (PMID 34212132, 2021). "The CXCL10/CXCR3 signaling pathway mediates paracrine interactions between tumor and stromal cells that govern leukocyte trafficking and angiogenesis." (PMID 34422627, 2021). "Pre-clinical modeling has shown that tumor-associated eosinophils express chemokines, such as CCL5, CXCL9, and CXCL10, which promote recruitment of tumor reactive CD8+ T cells into the tumor microenvironment." (PMID 34732251, 2021). "Th1 cells recruitment at tumor site can be enhanced by the epigenetically induced re-expression of endogenous retroviruses or Th1-attracting chemokines (CXCL9 and CXCL10) by tumor cells." (PMID 34262562, 2021). "CXCR3 is the predominant chemokine receptor mediating TE cells recruitment to tumor tissue via its ligands CXCL9 and CXCL10, and has been demonstrated to be crucial for tumor control and survival." (PMID 33466646, 2021). "Expression of CXCL10 was mainly found in the tumor cells and immune cells although some tumor stromal cells also showed a positive staining." (PMID 34504204, 2021).